MMP9 (matrix metallopeptidase 9)
Diseases named in the same sentence as MMP9 in open-access papers (continued):
Sharing a sentence is not in itself a finding about the gene and the disease.
tumor (continued). "Major tumor-promoting and immunosuppressive functions of myeloid cells include release of growth factors such as MMP-9 and oncostatin M which induce upregulation of VEGF and HIF-2alpha pathways leading to neo-angiogenesis, hypoxia, and ultimately cancer invasiveness and progression." (PMID 34531864, 2021). "The western blot results showed that in EO771 cells, A5 CM downregulated tumor-promoting genes such as Sclerostin, Lrp5, β-catenin, MMP9, Runx2, TGFβ, and Snail and elevated the level of an apoptosis marker, cleaved caspase 3, more substantially than did Y4 CM." (PMID 34230453, 2021). "Consequently, IL‐33‐induced macrophage MMP‐9 robustly mitigates the tumor killing‐effect by T cells." (PMID 34486239, 2021). "Moreover, the overexpression of MAPK pathways is linked with the overexpression of ERK, which leads to the overexpression of several genes involved in tumor development, including MMP9." (PMID 34069882, 2021). "Although the reduction of MMP2 was marginal, the reductions in FAK, mesenchymal markers, and MMP9 in Pgrmc1 KO mice may be considered as comprising a challenging environment for the migration of tumor cells." (PMID 33832499, 2021). "In addition, the activities of MMP2 and MMP9 were largely declined in tumor tissues in the sh-hsa_circ_0004712 group." (PMID 34507595, 2021). "Western blot showed that the protein expression levels of FSTL3, Vimentin, N-cadherin, MMP2 and MMP-9 in the mice tumor tissue in the sh-LBX2-AS1 experimental group were decreased, indicating that FSTL3 expression was increased at protein level and EMT was promoted." (PMID 34858481, 2021). "Finally, to evaluate the involvement of drug treatment on tumor invasiveness, we performed Western blot analyses of MMP-9 protein." (PMID 34108938, 2021). "Therefore, the study of the transcriptional regulation of MMP9 will be favorite to revealing its fine mechanism of action in tumor." (PMID 33430865, 2021). "Moreover, deletion of the MMP-9 gene has been reported to delay the tumor onset or suppressed tumor progression in many genetically engineered mouse models of cancers." (PMID 33828938, 2021). "G-MDSCs promote angiogenesis, produce high levels of MMP9 and augment tumor growth." (PMID 34572138, 2021). "Furthermore, EMT induced migration in tumour cells whereas MMP9 is a potential EMT-promoting factor." (PMID 33535172, 2021). "In addition, HSD17B6 overexpression suppressed the expression of MMP2 and MMP9, which are critical proteinases for tumor invasion and metastasis through degrading extracellular matrix and vascular basement membrane." (PMID 34750355, 2021). "Hence, agents with MMP-9 inhibitory activities would be an attractive candidate to combat skin aging." (PMID 34188145, 2021). "However, MMP-1, MMP-9 and TIMP-1 were more frequently expressed by stromal macrophages in BCC samples from immunocompetent individuals, emphasizing the role of the tumor microenvironment in BCC behavior in association with the patient’s immune status." (PMID 34204372, 2021). "Furthermore, a significantly larger peripheral MMP-9 area was observed in DH82-medium tumors at 63 dpt compared to untreated control neoplasms (p = 0.0002)." (PMID 33808256, 2021). "MMP, OXSR-1, TAC, FOXO-3 and MMP-9 were measured in tumour cell lysates by the ELISA technique." (PMID 34072756, 2021). "Furthermore, overexpression of MMP‐2 and MMP‐9 is closely correlated with tumor invasion and migration." (PMID 34531985, 2021). "In addition, neutrophils can enhance tumor growth through production of matrix metalloproteinase (MMP)-9 that inhibits tumor cell apoptosis in the respiratory tract and can increase tumor angiogenesis and neovascularization." (PMID 34660642, 2021). "MMP-9 that was highly expressed in the tumor microenvironment could hydrolyze the micelles, leading to a micelle-to-nanofiber transformation." (PMID 33718335, 2021).
tumor (continued). "Moreover, NETs promote metastasis by degrading the extracellular matrix (ECM) and releasing protease components such as matrix metalloproteinase 9 (MMP-9) that block tumor apoptosis." (PMID 34835236, 2021). "MMP-9 is shown to play an important role in tumor dissemination." (PMID 34771620, 2021). "Moreover, elevated levels of N-cadherin (CDH2), which increases the production of MMP9 to initiate the ideal environment for migratory tumour cells by rupturing the basement membrane in the tumour primary site, would eventually promote the migration process." (PMID 33073304, 2021). "Additionally, MMP9 can degrade type IV collagen and destroy the basement membrane, which is related to tumor invasion and metastases." (PMID 34607974, 2021). "We can speculate that overactivation of NRF2 caused by DLG domain MTs in Hepa1-6 and Huh7 cells leads to overexpression of MMP9 that enhances tumor cell invasion and metastasis." (PMID 34069882, 2021). "Numerous studies verified that MMP9 promoted tumor growth and metastasis in various cancers 59-61." (PMID 33758602, 2021). "Additionally, the levels of tumor-promoting genes (Lrp5, MMP9, Runx2, and Snail) were increased by TGFβ and CXCL5, while they were reduced by TPM4, ANXA6, and Trail." (PMID 34230453, 2021). "This might reflect the fact that male tumors were often larger in size, as MMP‐9 is needed for tissue destruction while the tumor is still growing, and that MMP‐8, and ‐9 may have mutual inducers in wound healing and related inflammation." (PMID 32985799, 2021). "In order to corroborate our findings on the pro-tumor effects of ILC2 CM for the migration and invasion of CRC, we evaluated in the SW116 line the expression of MMP9 and N-cadherin, two molecules that have been linked to the progression and invasion of tumor cells." (PMID 33953160, 2021). "As an important proteolytic enzyme, MMP-9 is involved in tumor invasion and metastasis." (PMID 33763485, 2021). "Our current findings are in line with the available reports wherein in vitro/in vivo models have shown that chrysin inhibits tumor metastasis by decreasing the expression of MMP9 and MMP2 as well as COX-2 and i-NOS, and modulates the PI3K/AKT signaling pathway." (PMID 35096000, 2021). "Also, the results of the analysis of tumor tissues revealed that the E-cadherin expression was upregulated, while the Slug, MMP-9, and vimentin expressions were down-regulated." (PMID 34073059, 2021). "In addition, matrix metalloproteinase (MMP-9) promotes tumor angiogenesis by increasing the expression of vascular endothelial growth factor (VEGFA) and its receptor (VEGFR)." (PMID 34955854, 2021). "Similarly, CCL21/CCR7 axis has been shown to promote MMP-9 release, stimulate tumor cell survival, adhesion, invasion, and metastasis in HNSCC." (PMID 33925575, 2021). "It is worth noting that, among the most overexpressed genes in OSCC cells is IL-8, another pro-inflammatory cytokine, and the matrix metallopeptidase 9 (MMP9), an enzyme related to tumor invasion, is associated with basement membrane degradation and extracellular matrix remodeling." (PMID 34202728, 2021). "In this way, MMP9 is involved in photoaging and radial growth phase of melanoma development and tumor angiogenesis, and its overexpression has been shown to significantly contribute tumor invasiveness and spreading, being related with metastasis and poor prognosis." (PMID 33809973, 2021). "Moreover, we detected the expression of LpCat1, STAT1, CyclinD1, ki67 and MMP-9 in the tumor tissues by immunohistochemistry." (PMID 34178664, 2021). "MMP-9 or gelatinase B is primarily found in saliva and gingival crevicular fluid; it is present in dental tissues with numerous active forms, weighing 82–132 kD, and is involved in inflammation, wound healing, and tumor growth." (PMID 33498206, 2021).
tumor (continued). "As a transcription factor with multidirectional regulatory function, NF-κB plays an important role in cell carcinogenesis and regulates the expression of its downstream target genes including MMP-9 and VEGF, which are closely associated with tumor genesis, metastasis and angiogenesis." (PMID 34059099, 2021). "Furthermore, PBMF treatment notably upregulated the mRNA expression levels of GSK-3β, E-cadherin, Bax, Caspase-3, and Caspase-9 but substantially downregulated those of β-catenin, N-cadherin, MMP-2, MMP-9, Snail, and Cyclin D1 in tumor tissues." (PMID 33964908, 2021). "Another study showed that negative Notch2 regulation induced by siRNA in gastric cancer cells increases the invasive function of tumor cells, enhances the expression and activity of MMP9, and increases the phosphorylation of the PI3K pathway, as with growing p-Akt was shown." (PMID 36643842, 2021). "MMP-9 accelerates the extravasation of VEGFR-1+ cells in the tumor niche." (PMID 34204372, 2021). "MMP-9 possess proteolytic properties against type IV collagen within the basement membrane, therefore might facilitate tumour invasion and metastasis in various tissues." (PMID 33990645, 2021). "The transition of TAMs into M2 state releases an abundant amount of transforming growth factor TGF-β, epithelial growth factor (EGF), matrix metalloproteinase MMP-2 and MMP-9, and IL-10, thus promoting tumor angiogenesis and invasion, as well as immune-suppressed microenvironment." (PMID 34439380, 2021). "Moreover, Salmonella was documented to downregulate the expression of certain oncoproteins in tumor cells including p-glycoprotein (p-gp) and matrix metalloproteinase 9 (MMP-9), inhibiting drug resistance and tumor metastasis, respectively." (PMID 34203478, 2021). "Moreover, lidocaine decreased tumor cells metastasis and MMP-9 formation and release by down-regulating Src-induced immune and inflammatory signaling pathway." (PMID 34249706, 2021). "Promoting tumour vasculature is another important role of MMP-9." (PMID 33802621, 2021). "Overexpression of MMP2 and MMP9 favour tumour recurrence in patients with stage T1 BC." (PMID 34142438, 2021). "It has been identified that MMP-9 plays a vital role in tumor development and progression." (PMID 33390772, 2021). "In addition, the overexpression of Lrp5 elevated Snail, MMP9, Runx2, and TGFβ and promoted the proliferation and invasion of 4T1Br tumor cells." (PMID 34031366, 2021). "Additionally, immunohistochemistry results showed that Ki-67 and MMP9 levels were decreased in sh-circ-CSPP1-transduced SW480 tumor tissues, demonstrating the repression of circ-CSPP1 knockdown on tumor cell proliferation and metastasis." (PMID 34124372, 2021). "MMP-9 is classified as a tumor biomarker and prognostic factor, and its regulation may become a therapeutic target." (PMID 34884588, 2021). "Evidently, NGAL is a new actor of tumor microenvironment that fosters cancer progression either as enhancer of MMP-9 activity or as iron transporter both in cancer and stromal cells given its ability to establish an articulated network between different tumor microenvironment cell populations." (PMID 34830212, 2021). "This particular subset could directly contribute to tumor growth and vascularization by producing MMP9 and differentiating into endothelial cells." (PMID 33538860, 2021). "MDSCs accumulated in TME produce MMP9 to promote tumor growth and tumor vasculature." (PMID 34359674, 2021).
tumor (continued). "Although only a small proportion of tumor cells showed increased MMP9 expression and tumor vessels showing decreased CLDN5 expression and low vascular tightness were distributed occasionally, extracranial metastasis likely occurs at a low frequency after a latent period of several years." (PMID 33799999, 2021). "Hence, increasing levels of MMP-9 correlates with tumor aggressiveness and also have a prognostic relevance in TNBCs." (PMID 34833068, 2021). "Likewise, they play a role in tumor cell migration by regulating the activity of proteins such as matrix metallopeptidase 9 (MMP9)." (PMID 33919272, 2021). "Interestingly, MMP2 and MMP9 are largely involved with hypoxia, tumor progression, and immune evasion." (PMID 34359789, 2021). "A wealth of evidence suggests that MMPs other than MMP-9 may be involved in tumor dissemination and metastasis." (PMID 34769032, 2021). "It was concluded that curcumin administered in combination with Glu-GNPs and X-ray irradiation could reduce the protein expression of VEGF, HSP90, HIF-1α, and MMP9 in tumor tissue when compared with the model group." (PMID 34825004, 2021). "MMP9 may also be associated with metastasis in CRC; high levels of both MMP1 and MMP9 expression in tumor-free mucosa correlated with TNM-stage and lymph node involvement." (PMID 33450835, 2021). "Additionally, FN1 was shown to induce MMP2 and MMP9 expression during the malignant progression of human cancers in previous studies, which was conducive to tumor migration, invasion, angiogenesis, and intravasation." (PMID 34758823, 2021). "As neutrophils can secrete immunosuppressive mediators and angiogenic factors such as reactive oxygen species, VEGF, (vascular endothelial growth factor) and MMP-9 (matrix metalloproteinase 9), neutrophil infiltration can contribute to a pro-tumor microenvironment." (PMID 33526794, 2021). "Meanwhile, the regulation of MMP9 activity was shown to be correlated with tumor cell invasion." (PMID 33889541, 2021). "MMP9 (matrix metallopeptidase 9) was identified as a prognostic tumor microenvironment–associated gene by using LASSO and TIMER (Tumor IMmune Estimation Resource) algorithms and was found to be positively correlated with immunosuppressive molecules and drug response." (PMID 33643387, 2021). "MMP-9 then induces degradation of the ECM to increase the migratory potential of the tumor cells." (PMID 34943937, 2021). "This shows a negative surface charge in the systemic circulation, exhibiting advantageous stability, accumulating at the tumor sites where MMP-9 is overexpressed, exposing the positively charged CPP following MMP cleavage, and resulting in enhanced internalization into target cells." (PMID 34689761, 2021). "Given that matrix metalloproteinase (MMP) family proteins and EMT-related proteins participate in tumor cell migration and invasion, we examined the transcript and protein level of MMP9, N-cadherin, Vimentin, and E-cadherin in cells with modified PLAGL2 expression levels." (PMID 33391500, 2021). "Furthermore, endothelial DLL4-mediated Notch signaling supports tumor cell invasion due to an increased MMP-9 expression by ECs." (PMID 34073394, 2021). "The results showed that IL-2, IL-12, IL-17, TNF-α, and INF-Υ, which were immunity promoting cytokines, were significantly upregulated in drug serum, while IL-10, TGF-β, VEGF, and MMP-9, which were immunity abating or tumor promoting proteins, were significantly downregulated in drug serum." (PMID 33505491, 2021). "The data presented that PCNA, MMP2 and MMP9 were all strikingly downregulated in the sh-hsa_circ_0004712 experimental group compared to the sh-NC control group, while the level of C-caspase 3 was opposite to them, suggesting that tumor growth was inhibited." (PMID 34507595, 2021).
tumor (continued). "Metformin is being investigated because its antineoplastic effects through AMPK-mediated or AMPK-independent inhibition of mTOR; it reduces cyclin D1 inhibiting cancer cell proliferation; it also inhibits tumor cell migration and invasion by inhibiting matrix metalloproteinase-9 (MMP-9) expression." (PMID 33807260, 2021). "There is overwhelming evidence that MMP-9 promotes cancer cell migration and tumor dissemination." (PMID 34769032, 2021). "Ki-67 is a standard marker of proliferation, and MMP9 is closely related to tumor cell metastasis." (PMID 34124372, 2021). "In addition to T cells, tumor-associated macrophages (TAMs) can produce VEGF and matrix metalloproteinase-9 (MMP-9), which promote angiogenesis, tumor invasion and metastasis, leading to a poorer prognosis." (PMID 33531980, 2021). "MMPs such as MMP-7 and MMP-9 have been found to promote tumor invasion in NSCLC metastasis." (PMID 33091333, 2021). "Moreover, TSP-1, which is secreted by tumour and stromal cells, inhibits MMP-9 and NO/cGMP-related pathways, which results in a limitation in their pro-angiogenic activity." (PMID 33923108, 2021). "Therefore, alteration of vascular wall stability and function through WNT signaling and MMP9 in icSFT/HPCs increases vascular permeability, infiltration of tissue around tumor cells, and distant metastasis." (PMID 33799999, 2021). "The migration marker MMP9 was measured by IHC and western blot in xenograft tumor tissue." (PMID 34218518, 2021). "IHC assay demonstrated that the protein levels of SLC1A5, Ki67 and MMP9 in tumor tissues were suppressed by the silence of circ-SFMBT2, indicating that circ-SFMBT2 could promote tumor proliferation and metastasis in mice." (PMID 34530825, 2021). "It has been reported that ropivacaine can block tumor cell invasion and MMP-9 secretion." (PMID 35280249, 2021). "In addition, the expression of invasive factors matrix metalloproteinase-2 and 9 (MMP2, MMP9) was increased in ascitic cells compared to cells from primary tumours." (PMID 34211089, 2021). "Likewise, MMP9 expression was downregulated by miR-1293 antagomir in tumor tissues of xenografted mice." (PMID 34616611, 2021). "Thus, MMP-9 is required for OSCC cells to cross the endothelium to complete tumor microenvironment and angiogenesis." (PMID 33828938, 2021). "In addition, results from western blotting indicated the expression of MMP-2 and MMP-9 proteins, which are great contributors to tumor cell migration, was significantly downregulated after the induction of RA in these two CC cell lines." (PMID 33621954, 2021). "However, both uPA and MMP-9 were shown to be independent prognostic factors, in addition to standard prognostic tumour features." (PMID 34439251, 2021). "Particularly, tumor-infiltrating NK cells expressed higher levels of VEGF, IL-8, matrix metallopeptidase 9 (MMP9), placental growth factor (PlGF) and angiogenin, which, collectively participate in tumor angiogenesis, tumor microenvironment remodeling and tumor growth." (PMID 34445750, 2021). "On the other hand, several subsets of hematopoietic progenitor cells (HPCs) recruited into the tumor bed act as peri-vascular modulators by producing growth factors, cytokines, and matrix metalloproteinase-9 (MMP9), a critical molecule for vascular remodeling and neovascularization." (PMID 34771577, 2021). "Nuclear import of HIF-1A as a transcription factor is a hallmark event in HIF-1 dependant hundreds of target gene activation, such as angiogenic gene including VEGF-A, Flt-1, ang-1, MMP-2 and MMP-9 which promotes tumour angiogenesis, metastasis and clinical prognosis." (PMID 33403040, 2021).